FGF23 (fibroblast growth factor 23)
Diseases named in the same sentence as FGF23 in open-access papers (continued):
Sharing a sentence is not in itself a finding about the gene and the disease.
hypophosphatemia (continued). "Renal phosphate wasting due to overproduction of fibroblast growth factor 23 (FGF-23) in dysplastic lesions may occur in nearly 50% of patients with FD/MAS and can lead to the development of hypophosphatemia and osteomalacia." (PMID 35420267, 2022). "Both XLH and primary hyperparathyroidism may feature hypophosphatemia, renal stone formation, elevated PTH and FGF23 levels." (PMID 33815294, 2021). "In particular, in case 2, because he strictly abstained from alcohol, the effect of alcohol consumption on the development of FGF23-related hypophosphatemia was not reconfirmed to date." (PMID 34901334, 2021). "Laboratory findings showed hypophosphatemia, elevated bone markers, and high serum FGF23 without renal tubular defects." (PMID 34797338, 2021). "In addition to genetic interventions, pharmacologic-based studies have shown that activation of FGFR1 induces FGF23 production and leads to hypophosphatemia, whereas the inhibition of FGFR signaling attenuates FGF23 production." (PMID 32982979, 2020). "Forced expression of human transgenic FGF23 has been shown to rescue the bone phenotype of Hyp mice, but not their hypophosphatemia." (PMID 30808384, 2019). "It has since become evident that hypophosphatemia-independent autocrine/paracrine effects of FGF23 can be mediated by calcitriol and tissue non-specific alkaline phosphatase (TNAP)." (PMID 30808384, 2019). "Finally, the relevance of FGF23 to bone abnormalities in XLH and other diseases of hypophosphatemia has been indicated by various animal experiments and clinical trials." (PMID 30808384, 2019). "Despite displaying hypophosphatemia and low serum calcitriol, mice with elevated FGF23 (Hyp or Fgf23-TG) did not develop skeletal abnormalities when CYP24A1 levels were repressed, either in Cyp24a1-null mutants or following blocking with CTA102." (PMID 30808384, 2019). "Increased levels of FGF23 lead to decreased TRP, hypophosphatemia and rickets." (PMID 29280738, 2017). "It is possible that longitudinal growth in HH patients reflects the individual severity of and response to a disturbed FGF23 homeostasis, rather than the severity of hypophosphatemia itself." (PMID 26543054, 2016). "Excess of both FGF-23 and PTH have been found to contribute to post-transplant hypophosphatemia." (PMID 24605319, 2014). "Our results demonstrate that activation of FGFR1, but not other FGFRs, is sufficient to induce FGF23 expression and the resulting hypophosphatemia in adult mice." (PMID 23451204, 2013). "In patients with humoral hypercalcemia of malignancy, and with metastatic ovarian cancer, FGF-23 concentrations are elevated without significant hypophosphatemia." (PMID 18288501, 2008). "One study demonstrated that FGF-23 concentration was elevated in patients with hypophosphatemia but was not increased in patients with normal Pi concentrations." (PMID 18288501, 2008). "In cases of CAO, in which FGF23 excess is caused by non-PMT solid or hematologic malignancies, the treatment approach involves targeting the underlying malignancy, while using medical therapies to manage the hypophosphatemia and symptoms." (PMID 39755803, 2025). "FGF23-mediated forms of hypophosphatemia can be suspected by non-suppressed FGF23 levels." (PMID 40295317, 2025). "Nonetheless, isolated reports showed that FGF23 staining was absent in the neural-derived tumour cells of neurofibroma as well as the resection of a large neurofibroma with increased uptake (as determined by 18FDG PET-CT scan) did not improve hypophosphatemia." (PMID 40133996, 2025). "The occurrence of hypophosphatemia following kidney transplantation is well described in the literature since during the initial post-transplant period, the accumulated plasma levels of PTH and FGF-23, together with the restored renal excretory capacity, stimulate phosphate excretion." (PMID 38384325, 2024).
hypophosphatemia (continued). "Elucidating the source of pathological FGF23 production in CSHS has important clinical consequences; nevi removal is both painful and associated with risk for patients, typically children, especially since evidence that it corrects hypophosphatemia is lacking." (PMID 36943390, 2023). "Genetic disorders of hypophosphatemia and a FGF23-secreting tumor were ruled out." (PMID 37908221, 2023). "Since FGF23 stimulates CYP24A1 and inhibits CYP27B1 (25-OH-D3 1α-hydroxylase) in kidney and extra-renal tissues, all FGF23-dependent OM, such as XLH, will have low calcitriol levels (despite hypophosphatemia), secondary hyperparathyroidism, and normal or low serum calcium." (PMID 37048797, 2023). "However, SFO has non-negligible risks of hypophosphatemia and fibroblast growth factor 23 (FGF23)-related osteomalacia." (PMID 35867202, 2022). "Consequently, hypophosphatemia and decreased calcitriol levels inhibit bone derived FGF23 secretion as a negative feedback control by diminishing VDR and extracellular phosphate signalling in the bone." (PMID 35269640, 2022). "However, a transgenic overexpression of Dmp1 failed to rescue elevated FGF23 levels and hypophosphatemia of Fam20c knockout mice, suggesting the involvement of other mechanisms." (PMID 36246908, 2022). "Therefore, we made a comprehensive diagnosis of PMT based on the biochemical characteristics of refractory hypophosphatemia, the imaging results of Tc99m-octreotide PET/CT scans, and FGF-23-positive expression on histopathology, after consulting with the MDT team." (PMID 36615052, 2022). "Finally, high normal FGF23 levels in the setting of hypophosphatemia should be interpreted as inappropriately normal and therefore do not exclude FGF23-driven hypophosphatemia." (PMID 34910242, 2022). "Also non-PMT malignant tumors can secrete FGF23 leading to hypophosphatemia with renal phosphate wasting." (PMID 35857061, 2022). "Since hypophosphatemia is induced by FGF23 but not by other ligands for FGFR1 —the main phosphate-regulating FGFR—cotreatment with recombinant FGF23 is one approach that could, in theory, mitigate this toxicity." (PMID 34007277, 2021). "In addition to changes in FGF23 levels, cotransporters and PTH receptor variations could also induce hypophosphatemia via disrupted phosphorus reabsorption metabolism." (PMID 33015068, 2020). "We postulate that the absence of rising FGF-23 levels in the acute phase following a decline in GFR may help counteract the development of further hypophosphatemia." (PMID 32634148, 2020). "The absence of this proteolytic activity in humans through the FGF23 gene mutations R176Q, R176W, R179Q, and R179W are causative for autosomal dominant hypophosphatemic rickets (ADHR), characterized by elevated intact FGF23 and hypophosphatemia." (PMID 32982979, 2020). "Nevertheless, FGF23 levels in CKD are elevated well above those observed in hereditary hypophosphatemia and at those concentrations FGF23 may reach toxic levels that are not relevant to XLH." (PMID 30808384, 2019). "FGF23 levels were raised, but a peripheral biologic resistance to FGF23 was hypothesized to account for the absence of a renal phosphate leak or hypophosphatemia." (PMID 29326910, 2017). "Additionally, hypophosphatemia blunts the production of parathyroid hormone (PTH) and fibroblast growth factor 23 (FGF23), releasing the inhibitory effect of both hormones on renal phosphate cotransporters (NaPi-IIa, NaPi-IIc and PiT-2), thus enhancing renal reabsorption of phosphate." (PMID 28662032, 2017). "The fact the serum phosphorus reduction in the cKO mice did not correlate proportionally to the elevation of serum FGF23 suggests that the hypophosphatemia in the Fam20C-deficeint subjects may not be fully dependent on the elevation of circulating FGF23." (PMID 28620244, 2017).
hypophosphatemia (continued). "Nevertheless, the dual inhibition of tubular phosphate reabsorption and 1α-hydroxylation of vitamin D observed during iron therapy, suggests that a phosphatonin hormone, fibroblast growth factor 23 (FGF23), may play a role in the hypophosphatemia induced by IV iron." (PMID 23902731, 2013). "Indeed, mice expressing high systemic levels of FGF-23 (R176Q) exhibit hypocalcemia and subsequent development of secondary HPT, even though their elevated PTH levels are likely to aggravate the prevailing hypophosphatemia." (PMID 21234310, 2010). "It is currently unknown why other iron preparations do not lead to the same extent of increase in FGF-23, although it is important to note that other iron infusions such as ferric derisomaltose and ferrumoxytol can also lead to hypophosphatemia, albeit less commonly and less severely." (PMID 41146174, 2025). "This clinical concern is exacerbated by the lack of consensus on if or how to treat FGF23-mediated hypophosphatemia, as treatment with phosphate supplementation can be counterproductive due to increased parathyroid hormone that may worsen FGF23-mediated urinary phosphate excretion." (PMID 40244590, 2025). "However, any diagnoses of FH coded in the study that were not XLH, including non-FGF23-mediated forms of hypophosphatemia, could not be excluded with the available data." (PMID 39539413, 2024). "Additionally, the diagnosis of CIH may not be accurate since this cohort did not have data on phosphate and FGF23 for evaluating the state of hypophosphatemia." (PMID 37635983, 2023). "However, since administration of a high phosphate diet ameliorates this phenotype, FGF23-induced hypophosphatemia rather than direct FGF23 actions on the brain might be involved." (PMID 29770125, 2018). "The results of our study challenge existing paradigms in mineral homeostasis; our data provide evidence that hypophosphatemia can develop in the absence of serum changes in the phosphaturic hormones, PTH and FGF-23 and despite declining serum Klotho levels." (PMID 32634148, 2020). "Also, special tests such as FGF23 or 1,25-(OH)2D, though highly informative for TIO work-up, may not be accessible for every clinician seeing patients with hypophosphatemia." (PMID 37980279, 2023). "In a subsequent study, however, FGF23 did not reduce serum phosphorus levels in double Fgfr3/Fgfr4 KO mice, suggesting that FGFR3 and FGFR4 play redundant roles in phosphate regulation, and perhaps that FGFR1 activation is not sufficient for FGF23 to induce hypophosphatemia." (PMID 23451204, 2013).
left ventricular hypertrophy (204 papers, 2010 to 2026). Enlargement of the LEFT VENTRICLE of the heart. "Left ventricular hypertrophy (LVH) is associated with increased cardiac expression of fibroblast growth factor-23 (FGF23) in mice and men." (PMID 41152461, 2025). "The phosphaturic hormone FGF-23 is another promising biomarker linked to left ventricular hypertrophy, myocardial fibrosis, and cardiovascular mortality, especially in renal dysfunction." (PMID 41226753, 2025). "Heart failure (HF) and left ventricular hypertrophy (LVH) are linked to fibroblast growth factor 23 (FGF23)." (PMID 40863356, 2025). "The increase in FGF23 levels is associated with cardiac fibrosis, left ventricular hypertrophy, and hypertension." (PMID 38530609, 2024). "Elevated FGF-23 is closely associated with increased cardiovascular risk, predicting adverse outcomes such as left ventricular hypertrophy, HF, and vascular calcification." (PMID 39273041, 2024). "The reason behind this association is the capability of FGF23 to induce inflammation, plus it is linked to vascular calcification and left ventricular hypertrophy in CKD patients." (PMID 39176315, 2024). "Increased levels of FGF23 have been associated with endothelial dysfunction, arterial wall calcification, left ventricular hypertrophy, coronary artery disease, unstable carotid atherosclerosis, and cardiovascular mortality." (PMID 38791495, 2024). "Recently, elevated FGF23 levels were found to be associated with adverse outcomes, such as vascular calcification, left ventricular hypertrophy, cardiovascular events, and increased mortality." (PMID 37605118, 2023). "Several studies showed FGF23 was independently associated with left ventricular hypertrophy, and there were many observational clinical reports on the positive correlation between FGF23 and vascular calcification in CKD patients." (PMID 37089720, 2023). "There is evidence that high levels of FGF-23 are linked to left ventricular hypertrophy (LVH), and cinacalcet lowers calcium levels, but it is impossible to say that lower levels of FGF-23 cause fewer cardiovascular events." (PMID 36812096, 2023). "Multiple epidemiological and patient studies have concluded that FGF23 acts directly on the myocardium or via elevations in blood pressure to cause left ventricular hypertrophy." (PMID 37334749, 2023). "There is biological plausibility for a causal relationship between FGF23 and left ventricular hypertrophy and atrial fibrosis, which is often observed in patients with AF38." (PMID 37798357, 2023). "Recent studies have provided evidence that a high plasma concentration of FGF23 is associated with cardiac disease, including left ventricular hypertrophy (LVH), heart failure, atrial fibrillation, and cardiac death." (PMID 36909314, 2023). "Fibroblast growth factor 23 (FGF-23) has been associated with left ventricular hypertrophy (LVH) and heart failure." (PMID 36790465, 2023). "Several studies have demonstrated an association for higher serum FGF23 levels with left ventricular hypertrophy, impaired vasoreactivity, and increased arterial stiffness." (PMID 36635269, 2023). "Specifically, it is suggested that exogenous erythropoietin generated by ESAs can largely increase C-terminal fibroblast growth factor 23 (FGF23) levels, which is significantly associated with left ventricular hypertrophy and an increased risk of mortality." (PMID 36170343, 2022). "Although elevated FGF23 levels are associated with a poor outcome in CKD (causing left ventricular hypertrophy), FGF23 also protects the body from the detrimental cardio-renal consequences of elevated Pi." (PMID 34994388, 2022). "FGF23 has been associated with congestive heart failure, left ventricular hypertrophy, and mortality." (PMID 36235716, 2022). "The next marker under consideration is fibroblast growth factor-23 (FGF-23), whose level is elevated in HD patients and is linked to left ventricular hypertrophy and increased mortality." (PMID 35206577, 2022).
left ventricular hypertrophy (continued). "High FGF23 plasma levels have been associated with increased mortality, HF and left ventricular hypertrophy." (PMID 35887917, 2022). "In both adult and pediatric CKD cohorts, higher FGF23 concentrations are independently associated with adverse clinical outcomes, including left ventricular hypertrophy and CKD progression." (PMID 35237863, 2022). "Continuously elevated serum FGF23 level can lead to AS and vascular dysfunction, promote left ventricular hypertrophy, and cause irreversible effects on cardiac function, leading to cardiorenal syndrome." (PMID 35546659, 2022). "Responses of FGF23, a phosphaturic hormone that has been linked to the development of left ventricular hypertrophy in CKD, are ambiguous." (PMID 34994388, 2022). "FGF23 is elevated in the early stages of nephritic damage, and as the renal disease progresses, plasma FGF23 levels continue to increase, and high levels of FGF23 cause left ventricular hypertrophy, renal function deteriorated, and increased mortality rate." (PMID 37674989, 2022). "A possible causal relationship was also described between FGF-23 and adverse cardiovascular remodeling, involving left ventricular hypertrophy, renin-angiotensin system upregulation and the promotion of vascular calcification." (PMID 35211520, 2022). "The elevated levels of circulating FGF23 are known as a risk factor for heart disease such as left ventricular hypertrophy, but further investigation is required to understand the underlying mechanism of FGF23 in this tissue." (PMID 35265628, 2021). "High FGF23 levels are associated per se with left ventricular hypertrophy and increased morbi-mortality, because of a direct toxic effect of FGF23 on cardiomyocytes." (PMID 34820344, 2021). "FGF23 is associated with the development of left ventricular hypertrophy (LVH) and thereby accounts to be a CVD risk factor in CKD." (PMID 34422725, 2021). "Enhanced fibroblast growth factor 23 (FGF23) is associated with left ventricular hypertrophy (LVH) in patients with chronic kidney and heart disease." (PMID 35118076, 2021). "Circulating FGF23 is associated with left ventricular hypertrophy and overall higher cardiovascular morbidity and mortality in CKD patients." (PMID 34290280, 2021). "FGF23 also correlated with MR indices confirming numerous clinical observations of the association of FGF23 and left ventricular hypertrophy." (PMID 33924991, 2021). "Although FGF23 mainly regulates phosphate homeostasis, in adults as well as in pediatric CKD the levels of FGF23 are markedly increased with progressing kidney failure and high FGF23 levels are strongly associated with left ventricular hypertrophy." (PMID 34422725, 2021). "Elevated levels of circulating FGF23 have been associated with left ventricular hypertrophy, and it has been suggested that FGF23 exerts a direct effect on the myocardium." (PMID 32235720, 2020). "The elevation of FGF-23 levels is associated with left ventricular hypertrophy in CKD3, and several possibilities have been postulated as the underlying mechanisms." (PMID 33060834, 2020). "High levels of FGF-23 have also been linked to left ventricular hypertrophy and mortality in patients with CKD." (PMID 32192220, 2020). "The increased fibroblast growth factor-23 level in CKD has been linked with left ventricular hypertrophy and increased left ventricular mass, resulting in left ventricular dysfunction." (PMID 31484322, 2019). "CKD often causes reduced bone mass and leads to left ventricular hypertrophy, a dangerous thickening of heart muscle related to over-production of the FGF23 hormone." (PMID 31044094, 2019). "Elevated FGF-23 is more closely associated to left ventricular hypertrophy and heart failure than atherosclerosis related CVD." (PMID 31246994, 2019). "Serum FGF-23 is associated with left ventricular hypertrophy and has been linked to an increased risk for cardiovascular mortality." (PMID 31014177, 2019).